IL6 (interleukin 6)
Diseases named in the same sentence as IL6 in open-access papers (continued):
Sharing a sentence is not in itself a finding about the gene and the disease.
tumor (continued). "In HCC tumor microenvironment, several cytokines and chemokines such as CXCL1, CSF1, CCL2, CCL9, IL-6, and IL-18 etc., which were secreted from either HCC cells or immune cells, promotes the recruitment and infiltration of MDSCs from the bone marrow into HCC tumor site 32-34." (PMID 33897880, 2021). "Tumor cells may also escape immune cells through the secretion of immunosuppressive factors, such as TGF-β and IL-6, as well as through the recruitment of Tregs." (PMID 34571731, 2021). "Conversely, IL6 blockade inhibited epithelial STAT3 activation and tumor growth in mice." (PMID 34944848, 2021). "It has been reported that M2-type TAMs contribute to the vascular proliferation of GBM cells by releasing insulin-like growth factor binding protein 1 (IGFBP1) and IL-6 to contribute to the expansion of tumor blood vessels in TME and the enhancement of blood supply to tumor tissues." (PMID 35095931, 2021). "The role of IL-6 in the induction of TAM-mediated CSCs has been studied by the inhibition of IL-6 with the anti-IL6-R antibody tocilizumab, which was able to decrease the number of the tumor spheres and chemoresistant cells." (PMID 33613850, 2021). "IL‐6 increases glucocorticoid levels in the serum, which may impair the infiltration and proliferation of CD8+ T cells within the tumor and weaken the therapeutic effects of PD‐1/PD‐L1 inhibitors." (PMID 33300678, 2021). "Indeed, among several cytokines that regulate the tumor-bone interaction and were upregulated significantly more by KLF5KQ than by KLF5KR (SHH, WNT5A, IL11, and IL6), the induction of IL-11 was dependent on CXCR4 expression." (PMID 33731701, 2021). "The Eμ-myc transgene increased the percent of immature double negative [DN] T cells in pre-tumor thymi, and this percent increased further in IL6-/-;Eμ-myc compared to IL6+/+;Eμ-myc mice." (PMID 33651821, 2021). "Mostly, autocrine or paracrine IL-6 regulated tumor progression and promoted the conversion of non-stem cancer cells into cancer stem-like cells through JAK/STAT3 signaling pathway." (PMID 34657635, 2021). "Furthermore, TMR with a glycolytic preference instills a “domino effect” by mediating the aggregation of various glycolytic and chemoresistance activators (VEGF, IL-1β, IL-8, IL-6, TGF-β, and lactate) within the tumor stroma." (PMID 34831136, 2021). "TAMs secreting IL-6, activating IL-6R/STAT3/miR-204-5p pathway of tumor cells." (PMID 34095111, 2021). "Results illustrated that STAT3 may be influenced during the tumorigenesis process of lung GGO as it is expressed higher in the tumor tissues than in normal lung tissues, while the trend of JAK1 seems to be consistent with that of IL-6." (PMID 34568032, 2021). "In particular, IL6 and BST2 were significantly induced in all naïve MSCs after 3 days’ coculture with primary tumor cells, whereas the expressions of ADAMTS12, MX2, LOXL2 and GREM1 varied and displayed transient induction during the course of the coculture assay." (PMID 34513701, 2021). "Such biochemical and cellular alterations may in turn result in an inflammatory local response potentially mediated by IL-6, IL-1β, and TNF-α, and inhibition of tumor growth." (PMID 34060472, 2021). "To evaluate the behavior of exosomes in such a cytokine milieu, we obtained exosome-depleted tumor interstitial fluid (TIF) from syngeneic, orthotopic EO771 cancer masses, which showed a range of cytokines and growth factors, including CCL2 and IL-6." (PMID 34112803, 2021).
tumor (continued). "IL-6 and IL-11 activate STAT3 through gp130, thus establishing an IL-6, IL-11/gp130/STAT3 signaling axis that prevents enterocytes from apoptosis, and facilitates cell survival and cell proliferation, ultimately promoting tumor growth." (PMID 34440220, 2021). "Additionally, IL-6 binds to its receptor IL-6R to regulating Janus kinase (JAK)/STAT3 signaling pathways, then stimulating the proliferation of tumor cells and the stemness of breast cancer stem cells (CSCs)." (PMID 33413697, 2021). "The tumor microenvironment is rich in stromal cells, such as fibroblasts, and those cells can be re-programmed due to the endocytosis of tumor-derived extracellular vesicles containing TGF-B1, TGF-B2, IL-6, MMP-2, and MMP-9." (PMID 34898576, 2021). "Plasma INFγ and IL-6 showed an increase due to the tumour while the other tested cytokines were not affected." (PMID 34732809, 2021). "Moreover, the targeted inactivation of IL-6, MCP-1/CCL2 or M-CSF has been shown to augment anti-tumor immunity and reverse resistance to immunotherapy." (PMID 34956864, 2021). "A total of 24 pyroptosis-related genes shown significantly different expression between normal and tumor tissues in COAD and seven genes (CASP4, CASP5, CASP9, IL6, NOD1, PJVK, and PRKACA) screened by univariate and LASSO cox regression analysis were used to construct the risk model." (PMID 34938319, 2021). "In particular, TGF-β1 and IL-6 generated by the TME components were shown to most likely contribute to the full feature establishment of T-MSCs, which in turn play an important role in tumor metastasis." (PMID 34513701, 2021). "IL-6 has been reported to induce PTP4A3 expression and to promote OvCa tumor cell migration." (PMID 34209460, 2021). "Additionally, MDSCs in EC TME can be recruited and activated by cancer cell-derived cytokines/chemokines (IL-6, IGFBP-3, CXCL16, and GM-CSF), thereby accelerating tumor progression by inhibiting CD8+ T cell activation." (PMID 33995371, 2021). "Cancer-associated fibroblasts, the most dominant components of the TME, are recipients of many of these factors (e.g., TGF-β), as well as directly contributing to tumor progression and an inflammatory TME via the secretion of VEGF, IL-6, IL-8, PGE2, TGF-β, and activation of NF-κB." (PMID 35047997, 2021). "Derived myeloid immunosuppressive cells (MDSCs) are also involved in tumor immunity which proliferate uncontrollably accumulating in TME as a result of signals of cytokines, such as G-CSF, GM-CSF, VEGF, MCP-1, and interleukins, such as IL-1β and IL-6." (PMID 34503196, 2021). "Additionally, TNFα is known to be a major inducer of chemokines such as CCL2 and IL-6 in the TME, thus increasing monocyte and macrophage infiltration as well as tumor growth and angiogenesis, respectively." (PMID 33540543, 2021). "The expression level of VEGFR and IL-6 in the sEV supplemented group had no noticeable change compared to the tumor-bearing control group." (PMID 34681680, 2021). "Intriguingly, p-STAT3 levels from bulk PDAC tumor samples do not significantly change between WT and IL-6 KO mice, nor in response to doxorubicin treatment at the times examined." (PMID 34711820, 2021). "For example, the absence of LAP would activate the STING signal pathway via the produced autoantigens (dsDNA) to induce pro-inflammatory gene expression (IL-6, TNF-α), polarizing TAMs into M1 macrophages and promoting the activation and differentiation of T cells to restrict tumor growth." (PMID 34956229, 2021). "Here, TAM primarily serves to promote tumor growth and progression via the generation of angiogenetic factors such as vascular endothelial growth factor (VEGF), and the secretion of immunomodulatory cytokines (e.g., IL-6, IL8 and IL-10)." (PMID 33430105, 2021). "Therefore, IL-6 can affect the stability of PD-L1 and its binding to PD-1 on immune cells through the IL-6/JAK1/STAT3 pathway, thereby mediating the immune escape of tumor cells." (PMID 34568032, 2021).
tumor (continued). "Noteworthy, the combined therapy with LCL-SIM and LCL-DMXAA strongly reduced (by 50–81%) the intratumor production of bFGF, IL-1 α/β, IL-6, TNFα, leptin and of eotaxin, which allow cancer cells to escape VEGF-targeted therapies, promoting tumor growth and metastasis." (PMID 34764332, 2021). "For example, in hepatocarcinoma, IL-6 promotes the expression of CD44+, inducing tumor development." (PMID 33613850, 2021). "These cells are capable of stimulating an antitumor immune response through presenting antigens to adaptive immune cells, producing proinflammatory cytokines such as IL-1β, IL-6, IL-12 and TNFα in addition to chemotactic factors such as IL-8 and MCP-1, as well as by phagocytosing tumour cells." (PMID 34944870, 2021). "In addition, pyroptosis activation in tumor cells by CAR-T cells leads to the release of DAMPs, such as HMGB1, that also trigger macrophages to release IL1β and IL6." (PMID 34685542, 2021). "Besides IL-6, IRF-8 was described as a key negative regulator of MDSC, as IRF8-/- mice display marked accumulation of MDSC in a tumor model." (PMID 33692788, 2021). "Tumor mitochondrial respiratory chain activity and content, particularly the integrated metric MHI, were consistently negatively correlated with IL-6 levels in ascites (p values = 0.042 to < 0.001); moreover correlations were up to an order of magnitude larger in ascites than in plasma." (PMID 34078919, 2021). "However, some studies have found that increasing the serum levels of IL-2, IL-6, IL-12, and TNF-α in tumour-bearing mice regulates the growth and differentiation of lymphocytes and activate macrophages, playing a regulatory role in antitumour immunity." (PMID 34801005, 2021). "In addition, CAFs can produce various tumor-promoting factors, such as IL-6, SDF-1α, and VEGF-A, in the metastatic tumor microenvironment." (PMID 34440886, 2021). "It has been demonstrated that 1,25(OH)2D may interfere with the production of tumor-derived signals that promote MDSC differentiation such as GM-CSF, IL-6, and miR155-containing exosomes." (PMID 34066482, 2021). "Bone marrow and spleen cells derived from tumor-bearing mice spontaneously released higher levels of IL-1β and IL-6 during 48 h in culture, compared to nontumor-bearing mice." (PMID 33649199, 2021). "A similar conclusion was obtained in a study of ginseng berry polysaccharide portion (GBPP), which stimulated macrophages to secrete anti-tumorigenic cytokines (e.g., IL-6, IL-12, TNF-α) while also promoting NK cells to release IFN-γ and granzyme B that inhibited tumor cells activities." (PMID 35002732, 2021). "M1-like macrophages were described as highly phagocytic and highly inflammatory and could facilitate anti-tumor immune response in the TME by secreting nitric oxide, reactive oxygen species (ROS), and inflammatory cytokines, including TNF-α, IL-1 and IL-6." (PMID 34512367, 2021). "In addition, MAFs secrete proinflammatory cytokines after activation, such as IL-6, IL-8 and IL-1β, and enhance the stemness and EMT phenotype of tumor cells to help them survive." (PMID 34112258, 2021). "Within the tumor microenvironment, GAM are forced to transform to M2 phenotypes by GBM cells that secrete factors such as IL-10, IL-4, IL-6, macrophage colony-stimulating factor, macrophage inhibitory factor, TGFβ, and prostaglandin E2, which subsequently supports tumor growth and invasion." (PMID 34267749, 2021). "In human ACP, the inhibition of IL6 (a SASP factor expressed in mouse and human ACP) results in reduced motility of ACP epithelial tumour cells, suggesting that SASP attenuation may reduce tumour burden in vivo." (PMID 34019103, 2021). "Like IL-6 and MCP-1, TGF-β exerts both tumor promoting as well as tumor suppressing roles." (PMID 34771568, 2021).
tumor (continued). "Since the onset of inflammation and carcinogenesis can be regulated by epigenetic events, we aimed to investigate the interplay among DNA methylation, miRNA expression, and gene expression of IL6, IL6R, including transmembrane isoform, and IL6ST in different tumor types." (PMID 34576335, 2021). "Notably, TAM acted directly on tumor cells and indirectly on the tumor microenvironment through cytokines, such as VEGF and IL-6, enhancing cancer cell invasion and metastasis, as well as angiogenesis." (PMID 33891564, 2021). "Indeed, the IL-6/STAT3 signaling pathway stimulates cell proliferation and migration/invasion, and protects tumor cells from drug-induced apoptosis." (PMID 34830463, 2021). "Similarly, it was reported that IL-6 expression in epithelium and stroma tissues of primary CRC was related to tumor invasion depth." (PMID 34576335, 2021). "MiR-19a mimic was also administered in the AOM/DSS-induced CRC mice and induced pro-inflammatory cytokines (IL-6, TNF-α, IL-1β and IL-17a), tumor proliferation marker (Ki-67) and NF-κB signaling markers (p-P65 and COX-2) via targeting TNF-α-induced protein 3 (TNFAIP3)." (PMID 33921348, 2021). "Studies have found that IL6 in the NB microenvironment is not derived from the tumor cells themselves, but is secreted by surrounding stromal cells, among which BMSC is closely involved as an important TME factor." (PMID 34790130, 2021). "Pro-inflammatory cytokines, such as interleukin-1 (IL-1), IL-6, IL-8, INF-γ, and TNF-α, favor tumor growth and invasion by promoting cell proliferation, epithelial-mesenchymal transition and angiogenesis, while increasing tumor immune surveillance." (PMID 34202728, 2021). "In addition, the miR-126 inhibitor obviously decreased the ratio of CD44+ CD90+ CD133+ cells, as well as the levels of IL-1α, SRY, Oct4, IL-6, and TGF-β in tumor tissues of mice." (PMID 34746322, 2021). "There are many papers concerning the influence of IL-6 on systemic and tumor iron level but not iron on IL-6 synthesis." (PMID 34681200, 2021). "Single sample GSEA (ssGSEA) of human PDA tumours adjusted for tumour purity, confirmed differential signalling pathway engagement where OSMRlhigh tumours display increased KRAS pathway activity, PI3K-AKT-mTOR and IL6-JAK-STAT3 signalling." (PMID 34921158, 2021). "Preclinical studies indicate increased IL‐6/JAK/STAT3 signalling in tumour cells and tumour infiltrating immune cells could promote tumour proliferation, survival, invasion and metastasis, and might suppress anti‐tumour immunity." (PMID 33382511, 2021). "Furthermore, IL‐6, IL‐7, IL‐8, and TGF‐β1 Abs (10 μg/mouse twice times per week, i.v.)markedly inhibited activated CAFs‐induced KYSE30 tumor malignancy in vivo." (PMID 34459125, 2021). "Next, we tested the efficacy of co-administration of α-IL-6 and α-CTLA-4 on lung orthotopic model in which LLC cells were inoculated percutaneously into the left lateral thorax, and the tumor nodules in the right lungs of injected mice were considered as metastatic lesions." (PMID 34093869, 2021). "It has been reported that adipose tissues, in which tumors have a predilection to grow, can convert tumor-suppressive NK cells to tumor-promoting cells through decreasing NK-mediated cytotoxicity and IFN-γ secretion and increasing IL-6 secretion, aiding tumor growth and expansion." (PMID 34638560, 2021). "In another in vitro study, IL-6 induced an epithelial-mesenchymal transition (EMT) phenotype in four ER-positive cell lines, through for example, down-regulation of E-cadherin, a membrane adhesion molecule involved in the mobilization of tumor cells." (PMID 34944905, 2021). "In the tumor microenvironment, CAFs interact with other cells through direct cell-to-cell contact and by secreting cytokines such as TGFβ1, epidermal growth factor (EGF), hepatocyte growth factor (HGF), and interleukin 6 (IL-6)." (PMID 34095135, 2021).
tumor (continued). "Increasing levels of VEGF, IL-6 and Regulated on Activation Normal T Cell Expressed (RANTES) were detected in PMPs isolated from patients with gastric cancer suggesting that PMP-shedding contributes to tumor angiogenesis." (PMID 34322381, 2021). "A similar result has been observed in treatment with IL-6 inhibitors and its receptor where preclinical trials showed antitumor efficacy against different tumor types, but the clinical trials do not seem to show good results." (PMID 33059744, 2020). "On the other hand, only mHCT116 tumor hosts saw significant elevations in circulating IL6 levels with respect to the sham mice (P<0.05); no changes were detected in the HCT116 hosts." (PMID 31915140, 2020). "Additionally, CXCR6high tumor cells in HCC can secrete cytokines such as IL-1β, IL-6, and IL-8, induce the infiltration of CD66b+ neutrophils, and promote neutrophil-mediated multiple protumor responses." (PMID 32770081, 2020). "As with the tumor itself, TME also responds to RT by inducing the release of pro-inflammatory cytokines and other molecules, including PDGF, IL1β, TNFα, TGFβ, C-X-C motif chemokine 12 (CXCL12), MMPs, IL6, EGF, and VEGF." (PMID 32660072, 2020). "Similarly, breast cancer exosomes were found to induce macrophage-mediated secretion of the cytokines TNFα, IL6, and MCP1, which stimulate tumor progression and metastasis." (PMID 32547552, 2020). "Chemotherapy drugs, the tumor itself, and the patient's long-term physiological and psychological stress can lead to increased production of inflammatory cytokines such as tumor necrosis factor alpha (TNF-α), interleukin 1 (IL-1), and interleukin 6 (IL-6)." (PMID 32684930, 2020). "However, IL‐6 also plays key role in the activation, proliferation, and survival of CD8+ T cells to paly anti‐tumor function." (PMID 32810392, 2020). "In this line, a recent study demonstrated high expression of cachexia-inducing factors, such as CXCL8, IL6, IL1B, CCL2, and TNF, in pancreatic cancer patients, whose tumor was classified as of low-purity (higher proportion of immune cells than of malignant cells)." (PMID 33604297, 2020). "M1 macrophage-related genes include IL-6, IL-8, CD80, PIM1, RTP4, and SLC11A1, and studies have shown that after metformin treatment, the expression of M1-related factors in tumor cells can be enhanced or weakened, thus affecting the prognosis of the tumor." (PMID 33193731, 2020). "This construct effectively neutralized macrophage-derived IL-6 without compromising anti-tumor efficacy." (PMID 33643299, 2020). "Although STC1 plays a pro‐oncogenic role in tumour progression, the counteracting effects STC1 on the pro‐inflammatory effects of IL6 and IL8 might slow down the process of carcinogenesis as the tumour grows." (PMID 32468698, 2020). "In addition, the cytokines IL-1α, IL-1β, IL-6, IL-17A, and TNF-α promote tumor initiation, progression, angiogenesis, and metastasis in many human malignancies, including CRC, and our findings are consistent with previous studies." (PMID 33488574, 2020). "In summary, the study shows that IL10 can inhibit the growth of transplanted tumor in vivo and the main mechanism may be the IL10-medited indirect inhibition of pro- inflammatory cytokines IL6 and TNF-α secretion and tumor angiogenesis." (PMID 32742480, 2020). "Inhibition of the NF-κB pathway by using tetrathiomolybdate, a specific copper chelator, or by transfecting a dominant-negative IκBα vector reduced the secretion of VEGF, fibroblast growth factor 2 (FGF2), IL-1α, IL-6, and IL-8 in vitro and SUM149 tumor growth and angiogenesis in vivo." (PMID 32883032, 2020). "For THP-1 and HL-60 cells alone without tumor cell supernatants, only IL6, IL8, TGFβ, and VEGF were found." (PMID 32316245, 2020). "Cross-linking and tumour antigen-specific IgE antibody-dependent cellular cytotoxicity (ADCC) of cancer cells by cancer patient-derived monocytes triggered release of pro-inflammatory mediators (TNFα, MCP-1, IL-10, CXCL-10, IL-1β, IL-6, IL-23)." (PMID 33203088, 2020).